HGF (hepatocyte growth factor)
Diseases named in the same sentence as HGF in open-access papers (continued):
Sharing a sentence is not in itself a finding about the gene and the disease.
Fulminant hepatitis (10 papers, 2011 to 2025). Acute hepatitis complicated by acute liver failure with hepatic encephalopathy occurring less than 8 weeks after the onset of jaundice. "The clinical trial NCT00225901 investigated the safety and efficacy of rh-HGF in patients with fulminant hepatitis." (PMID 40304568, 2025). "On the clinical side, a trial (NCT00225901) has investigated the safety and efficacy of recombinant human HGF (rh-HGF) in patients with fulminant hepatitis." (PMID 40304568, 2025). "Serum HGF is elevated in fulminant hepatitis, and its measurement is known to be useful in predicting fulminant hepatitis and its prognosis." (PMID 37640752, 2023). "HGF strongly induces DNA synthesis in hepatocytes and correlates with the progression of HE in patients with fulminant hepatitis, reflecting their prognosis." (PMID 37941897, 2023). "Hepatocyte growth factor (HGF) was originally discovered in the serum of patients with fulminant hepatitis due to its strong capacity to induce hepatocyte proliferation." (PMID 33925510, 2021). "Exogenous administration of recombinant HGF protein suppresses lipopolysaccharide-induced or Fas-mediated mouse models of fulminant hepatitis." (PMID 30083132, 2018). "In phase I/II clinical trials, intravenous administration of HGF protein was well tolerated by patients with fulminant hepatitis." (PMID 28548072, 2014). "In preclinical models for fulminant hepatitis, systemic administration of recombinant HGF suppressed the onset of fulminant hepatitis." (PMID 28548072, 2014). "Human hepatocyte growth factor (HGF) is an endogenously expressed bioactive substance that was originally discovered in the serum of fulminant hepatitis patients because of its powerful ability to induce hepatocyte proliferation; thus, it was originally recognized as a hepatocyte growth factor." (PMID 31013780, 2019). "We performed a translational medicine protocol with recombinant human HGF (rh-HGF), including a phase I/II study of patients with fulminant hepatitis (FH) or late-onset hepatic failure (LOHF), in order to examine the safety, pharmacokinetics, and clinical efficacy of this molecule." (PMID 21548996, 2011).
hearing loss (10 papers, 2012 to 2025). "HGF/MET signaling has been suggested to play a role in VS-related hearing loss and excessive HGF up- or down-regulation was associated with deafness of patients." (PMID 37627117, 2023). "A recent example of such a study is illustrated by efforts to understand human hearing loss associated with deletions in the 3′ UTR of hepatocyte growth factor (HGF)." (PMID 34093131, 2021). "More surprisingly, the only disease in humans associated with mutations in HGF is non-syndromic hearing loss." (PMID 34093131, 2021). "Additionally, the association of elevated HGF levels with lower WR scores indicates that HGF not only plays a role in the pathobiology of VS, as we previously demonstrated, but also in VS-associated hearing impairment." (PMID 39923035, 2025). "Our finding of elevated levels of TNF-α, IL-2R, CD163, eotaxin, and HGF in VS-CM being significantly associated with hearing impairment in patients with VS suggests that inflammatory pathways and immune cell activation are key contributors to VS-induced hearing loss." (PMID 39923035, 2025). "In addition, the HGF/MET signaling pathway is involved in VS pathogenesis including hearing loss." (PMID 37627117, 2023). "Conversely, the ubiquitous overexpression of HGF in a transgenic mouse resulted in progressive hearing loss associated with a degeneration of the outer hair cells; therefore, the dysregulation of HGF might be involved in nonsyndromic hearing loss." (PMID 28548072, 2014). "Although MACC1 expression is associated with highly malignant tumors and VS are considered benign, both are attached to the HGF/MET signaling pathway and MACC1 is a candidate gene localized at a hearing loss-related gene locus." (PMID 37627117, 2023). "Consistently, a similar type of hearing loss has also been associated with many variants in TECTA, MYO7A, HGF, and POU3F4 in previous reports." (PMID 33976695, 2021). "A strong evidence of HGF-MET axis importance in the human development of nervous system comes from some studies that reveal a genetic implication of HGF and MET genes in some NDDs such as autism spectrum disorder (ASD), schizophrenia, and non-syndromic hearing loss." (PMID 34179015, 2021). "Specifically, non-coding mutations of HGF are associated with non-syndromic hearing loss, autosomal recessive deafness-39 (DFNB39), while a mutation in MET is associated with human DFNB97 hearing loss." (PMID 31185063, 2019). "More and more studies have shown that defects in the HGF/c-MET signaling pathway can lead to the inability of melanocytes to successfully integrate the intermediate cell layer, resulting in hearing impairment." (PMID 41411333, 2025). "Interestingly, HGF has also been shown to stimulate receptor kinase activity in both osteoclasts and osteoblasts, which could be a potential explanation for elevated bone ALP, and mutations in HGF have been shown to lead to hearing loss." (PMID 22912808, 2012).
Hepatic steatosis (10 papers, 2013 to 2025). Steatosis is a term used to denote lipid accumulation within hepatocytes. "Disruption of VLDL secretion is likely an important mechanism underlying alcoholic fatty liver, because improvement of VLDL secretion was associated with attenuation of alcoholic fatty liver by zinc, betaine or hepatocyte growth factor." (PMID 23405143, 2013). "Interestingly, the underlying mechanism of attenuated hepatic steatosis by blocking mineralocorticoid receptor is mediated through the HGF-MET pathway." (PMID 30083132, 2018). "The temporal relationships among these parameters suggest that hepatic steatosis and hepatomegaly secondary to the Sch B-induced increase in serum TG level may be causally related to an increase in HGF release and/or production." (PMID 28086886, 2017). "HGF/NF-κB/SNARK was downregulated in HFD-fed rats receiving AICAR with improved hepatic steatosis and reduced inflammatory cytokines and oxidative stress." (PMID 36834782, 2023). "At the same time, changes such as hepatomegaly, high serum HGF level and hepatic steatosis were also observed in Sch B-treated mice." (PMID 28086886, 2017). "The same group later reported that 7 days of HGF treatment at a dose of 200 μg/kg also could reverse alcohol-induced fatty liver by enhancing lipid secretion from hepatocytes." (PMID 32372975, 2020). "Since our data clearly showed that exogenous HGF treatment efficiently reduced the fat content in the liver and inhibited CDAA diet-induced lipogenesis in mice, further evaluation in large animals may be needed to determine the efficacy and safety of HGF in fatty liver disease." (PMID 30083132, 2018). "In our resent study on hepatic steatosis induced by TPN using rats, the administration of HGF was effective." (PMID 34448078, 2021). "In diseases with exacerbated cell death, such as hepatic steatosis, one might restore the balance by favoring MET pro-survival signaling with ectopic HGF/SF treatment." (PMID 32091387, 2020).
keratoconus (10 papers, 2013 to 2026). A degenerative, structural disorder of the eye, characterized by a cone-shaped protrusion of the cornea. "Variants in the HGF gene region (encoding hepatocyte growth factor) have been reported in multiple cohorts—for example, a SNP upstream of HGF (rs3735520) was associated with keratoconus in studies from the USA, Australia, and Europe." (PMID 41595486, 2026). "Several HGF variants have been associated with keratoconus, and even increased HGF protein expression within corneal epithelium has been reported for keratoconic patients." (PMID 30863626, 2019). "A previous study has indicated suggestive association of the hepatocyte growth factor (HGF) gene with Keratoconus." (PMID 24416191, 2014). "Using GWAS, Burdon and colleagues identified a SNP (rs3735520) at the HGF (OMIM 142409) locus to be associated with keratoconus in cohorts from Australia, USA, and Northern Ireland." (PMID 25254113, 2014). "Recently, association of keratoconus with the hepatocyte growth factor, HGF, and the microRNA MIR184 genes was identified." (PMID 23592923, 2013). "Logistic regression analysis for the assessment of the Hepatocyte Growth Factor (HGF) Gene with corneal curvature and keratoconus." (PMID 24416191, 2014). "Similarly, other candidate genes identified by GWAS including HGF, RAB3GAP1, LOX, MPDZ, NFIB, BANP, and ZNF469 may be important risk factors for keratoconus and require replication studies in other populations." (PMID 25254113, 2014).
leiomyosarcoma (10 papers, 2005 to 2023). An uncommon, aggressive malignant smooth muscle neoplasm, usually occurring in post-menopausal women. "The authors tested Met-pep1 labeled with125I as a diagnostic tracer in vivo in xenografts in mice models of human leiomyosarcoma derived from the cell line SK-LMS-1/HGF, which expresses c-MET/HGF." (PMID 28485003, 2017). "Cases with 2+ HGF staining intensity were also seen in leiomyosarcomas, MPNST and clear cell sarcomas." (PMID 25844809, 2015). "HGF overexpression was seen in undifferentiated pleomorphic sarcomas (12/36, 33%), angiosarcomas (6/39, 15%), clear cell sarcomas (2/13, 15%), malignant peripheral nerve sheath tumors (3/24, 13%), leiomyosarcomas (5/68, 7%) and GIST (1/126, 0.8%)." (PMID 25844809, 2015). "In leiomyosarcoma-derived cell lines it could be demonstrated that hepatocyte growth factor (HGF) induces a decrease in anti-angiogeneic THBS1 and an increase in VEGFA." (PMID 24398114, 2014). "Furthermore, recent observations by Zhang and coworkers point to an important function for STAT3 in both tumorigenesis and metastasis formation in leiomyosarcoma, due to signaling by hepatocyte growth factor/scatter factor." (PMID 15647107, 2005). "6% of the tumors showed hepatocyte growth factor overexpression, mainly seen in undifferentiated pleomorphic sarcomas and angiosarcomas, but also in clear cell sarcomas, malignant peripheral nerve sheath tumors, leiomyosarcomas and gastrointestinal stromal tumors." (PMID 25844809, 2015). "The leiomyosarcoma cell line SK-LMS1, which also has autocrine HGF/Met signaling, and the clear cell renal cell carcinoma cell line UOK331 provided unambiguous positive and negative controls for DATE region truncation, respectively." (PMID 36672409, 2023).
Myocardial fibrosis (10 papers, 2011 to 2025). "Hepatocyte growth factor (HGF), a versatile factor governing cell growth, motility, and morphogenesis, acts as an inhibitor of myocardial fibrosis." (PMID 39239656, 2024). "Specifically, HGF markedly attenuates myocardial fibrosis by decreasing matrix metalloprotease 2 and 9 expression levels and by inhibiting the formation of collagens I and III20." (PMID 27804974, 2016). "Under echocardiography guidance, intramyocardial injection of transfected HGF with BMSCs can enhance cell survival, improve cardiac function, stimulate angiogenesis, and reduce myocardial fibrosis in a post-MI rat model." (PMID 27804974, 2016). "They found that the release time of HGF hydrogel was prolonged and the expression of genes related to myocardial fibrosis and angiogenesis was upregulated, which inhibited myocardial fibrosis, promoted angiogenesis, and improved the cardiac function of the rat." (PMID 37840964, 2023). "Herein, we hypothesized that combined treatment with HGF and BMSCs can stimulate cardiac repair and attenuate myocardial fibrosis through synergistic effects." (PMID 27804974, 2016). "The therapeutic benefit of combined treatment could be due to the direct inhibitory action of myocardial fibrosis by both HGF and BMSC transplantation." (PMID 27804974, 2016). "Our data suggested that transfection of HGF into BMSCs for MI treatment could significantly improve LV function, stimulate microvessel angiogenesis, enhance cardiomyocyte regeneration, and inhibit myocardial fibrosis compared with BMSCs or HGF injection alone." (PMID 27804974, 2016). "Thus, the specific aim of our study was to investigate whether the combination of BMSCs and HGF therapy could synergistically improve cardiac function, stimulate endogenous neovascularization and attenuate myocardial fibrosis after MI." (PMID 27804974, 2016). "Guohua et al37 found that HGF inhibited AngII‐induced CTGF the expression in rat fibroblasts and improved myocardial fibrosis." (PMID 30697920, 2019).
pneumonia (10 papers, 2005 to 2023). An acute, acute and chronic, or chronic inflammation focally or diffusely affecting the lung parenchyma, caused by an infection in one or both of the lungs (by bacteria, viruses, fungi, or mycoplasma.). "After establishing that mouse neutrophil elastase cleaves mouse HGF in vitro, we tested our predictions in vivo by examining lung pathology and HGF in mice infected with Mycoplasma pulmonis, which causes neutrophilic tracheobronchitis and pneumonia." (PMID 25938594, 2015). "Serum HGF levels in patients with Legionella pneumonia were higher than in those with pneumonia caused by other pathogens." (PMID 21429184, 2011). "HGF levels increased in severer pneumonia caused by Legionella, suggesting that HGF might play a significant role in the Legionella pneumonia." (PMID 21429184, 2011). "Serum HGF levels are considered to be associated with the response of pneumonia to antimicrobials." (PMID 21429184, 2011). "In conclusion, our study showed that HGF levels increased in severer pneumonia caused by Legionella, and suggested that HGF might play a significant role in the Legionella pneumonia." (PMID 21429184, 2011). "Elevated concentrations of both pro- and anti-inflammatory plasma cytokines were observed in the pneumonia group, including G-CSF, HGF, IL-1b, IL-1RA, IL-2, IL-2Ra, IL-6, IL-10, IL-18, IP-10, monocyte chemoattractant protein-3 (MCP-3), and TNF-α." (PMID 36119044, 2022). "At the site of infection, a local production of HGF has been found during bacterial meningitis and pneumonia." (PMID 15826299, 2005). "Also coinciding with pneumonia are elevated levels of hepatocyte growth factor (HGF) which exhibits high affinity to sulfated glycan." (PMID 30208953, 2018). "The factors influencing increased serum HGF levels in Legionella pneumonia might include severer form of the pneumonia and complication of liver dysfunction." (PMID 21429184, 2011). "Low amounts of serum HGF in patients with pneumonia correlated significantly to poor prognosis." (PMID 15826299, 2005). "In patients with pneumonia, the IL-6, IFN-γ, G-CSF, M-CSF, IL-1Ra, IL-2Ra, IL-10, HGF, MCP-1, and MCP-3 expression levels showed a strong positive correlation." (PMID 35382755, 2022). "This study reveals fragmentation of HGF into NK4-like proteins in mice with mycoplasma-induced neutrophilic tracheobronchitis and pneumonia, thereby providing in vivo evidence of HGF antagonist generation in lung tissues." (PMID 25938594, 2015). "One study demonstrated that serum HGF levels were lower in severe pneumonia than in non-severe pneumonia." (PMID 21429184, 2011). "The present study tested this hypothesis in mice by exploring selective hydrolysis of mouse HGF by mouse mast cell- and neutrophil-derived proteases in vitro and by examining HGF and NK4-like fragments in protease-deficient mice with and without pneumonia." (PMID 25938594, 2015).
asthma (9 papers, 2014 to 2025). "In a mouse model of asthma, exogenously administered HGF decreased airway remodeling associated with allergen challenge, and antagonism of endogenous HGF increased airway responsiveness to bronchoconstrictors." (PMID 25938594, 2015). "HGF has been suggested to suppress airway hyper-responsiveness, inflammation, remodeling, and eosinophil function in asthma." (PMID 24604303, 2014). "MET acts as a receptor for hepatocyte growth factor, and when hepatocyte growth factor binds to the MET receptor, it initiates intracellular signaling events that are crucial in asthma." (PMID 38275403, 2024). "Here, we have analyzed the levels of cytokines such as IL-13, IFN-γ, TNF-α, IL-4, IL-5, and IL-1β and growth factors such as HGF, VEGF, and CSF2 or GM-CSF along with the estimation of serum S1P concentration in asthma patients compared with the healthy controls." (PMID 32637407, 2020). "Similarly, the growth factors that were found to be upstream of S1P signaling such as HGF, VEGF, and CSF2 were significantly (P < 0.01) increased in the serum of asthma patients compared to the healthy controls." (PMID 32637407, 2020). "In addition, IMD-4690 strongly inhibited airway remodeling by regulating the production of remodeling-related mediators (i.e., TGF-β, VEGF, and HGF) and enzymes (i.e., MMP9) in a chronic antigen exposure mouse model of asthma with Dp." (PMID 25785861, 2015).